RNY1P5 (RNY1 pseudogene 5)
Gene: Miscellaneous RNA gene on chromosome 13 (74,289,100 to 74,289,214, reverse strand). Ensembl gene ENSG00000206617.
Homologues: Orthologues: chimpanzee Y_RNA (100% identical), macaque Y_RNA (95% identical), guinea pig Y_RNA (90% identical). Paralogues in human: Y_RNA (90% identical), Y_RNA (87% identical), Y_RNA (85% identical), RNY1 (84% identical), Y_RNA (84% identical), Y_RNA (83% identical), RNY1P1 (83% identical), Y_RNA (82% identical), RNY1P11 (81% identical), Y_RNA (81% identical), RNY1P8 (80% identical), Y_RNA (80% identical), and 96 more.